VWC2 (von Willebrand factor C domain containing 2)
Description:
BMP antagonist which may play a role in neural development. Promotes cell adhesion (By similarity).
Synonyms: PSST739; UNQ739
Tractability: Antibody: UniProt places it where antibodies can reach, with medium confidence; UniProt predicts a signal peptide or a membrane-spanning region; its Gene Ontology location is reachable by antibodies, with medium confidence.
Gene: Protein-coding gene on chromosome 7 (49,772,822 to 49,921,950, forward strand). Ensembl gene ENSG00000188730.
Subcellular location: Secreted, extracellular space, extracellular matrix, basement membrane; Synapse
Gene Ontology:
Molecular function: protein binding
Biological process: negative regulation of BMP signaling pathway; positive regulation of neuron differentiation; neurotransmitter receptor localization to postsynaptic specialization membrane
Cellular component: AMPA glutamate receptor complex; extracellular region; basement membrane; extracellular matrix; extrinsic component of postsynaptic membrane; glutamatergic synapse; interstitial matrix; synapse
Genetic constraint (gnomAD): Loss-of-function variants: 14 observed, 19.88 expected, observed/expected ratio (o/e) 0.7, 90% interval 0.46 to 1.1. The synonymous counts are far from expectation, so gnomAD's model fits this gene poorly and the ratio says little. Missense variants: 457 observed, 369.65 expected, observed/expected ratio (o/e) 1.24, 90% interval 1.14 to 1.34. Synonymous variants: 213 observed, 154.56 expected, observed/expected ratio (o/e) 1.38, 90% interval 1.23 to 1.54.
Homologues: Orthologues: chimpanzee VWC2 (99% identical), macaque VWC2 (99% identical), pig VWC2 (92% identical), dog VWC2 (91% identical), mouse Vwc2 (91% identical), guinea pig VWC2 (87% identical), rat Vwc2 (79% identical), tropical clawed frog vwc2 (66% identical), zebrafish vwc2 (53% identical). Paralogues in human: VWC2L (35% identical), MUC5B (22% identical), MUC5AC (21% identical), OTOG (20% identical), OTOGL (20% identical), CHRDL1 (19% identical), CHRDL2 (19% identical), MUC2 (19% identical), VWF (19% identical), FCGBP (19% identical), KCP (17% identical), CRIM1 (17% identical), and 7 more.
Diseases named in the same sentence as VWC2 in open-access papers:
VWC2 is named in the same sentence as 4 diseases in open-access papers, as found by Europe PMC text mining. Sharing a sentence is not in itself a finding about the gene and the disease. The quoted sentences say what the papers report.
Stroke (1 paper, 2025). Sudden impairment of blood flow to a part of the brain due to occlusion or rupture of an artery to the brain. "Ten proteins (including BCAN, NCAN, beta-NGF, SIGLEC1 and VWC2) were common to both the acute and convalescent stroke phase, but there were also differing examples." (PMID 40316737, 2025).
cancer (2 papers, 2015 to 2017). A tumor composed of atypical neoplastic, often pleomorphic cells that invade other tissues. "DNA methylation alterations in UNC13A, SP9, GP5, C1QL3, SP8, and VWC2 have not been previously reported in cancer." (PMID 26380585, 2015).
VWC2 also shares sentences with these, for which no sentence is quoted: colon cancer (1 paper); tumor (1).